ZFAND2A (zinc finger AN1-type containing 2A)
Synonyms: AIRAP
Tractability: PROTAC: ubiquitination databases record sites on it.
Gene: Protein-coding gene on chromosome 7 (1,151,903 to 1,160,771, reverse strand). Ensembl gene ENSG00000178381.
Subcellular location: Cytoplasm; Nucleus
Gene Ontology:
Molecular function: protein binding; zinc ion binding
Biological process: proteasome-mediated ubiquitin-dependent protein catabolic process; protein targeting to ER
Cellular component: endoplasmic reticulum; cytoplasm; nucleus; proteasome complex
Genetic constraint (gnomAD): Loss-of-function variants: 18 observed, 11.34 expected, observed/expected ratio (o/e) 1.59, 90% interval 1.07 to 1.94. The synonymous counts are far from expectation, so gnomAD's model fits this gene poorly and the ratio says little. Missense variants: 227 observed, 188.73 expected, observed/expected ratio (o/e) 1.2, 90% interval 1.08 to 1.34. Synonymous variants: 92 observed, 62.87 expected, observed/expected ratio (o/e) 1.46, 90% interval 1.24 to 1.74.
Homologues: Orthologues: macaque C3H7orf50 (96% identical), dog ZFAND2A (84% identical), guinea pig ZFAND2A (82% identical), mouse Zfand2a (77% identical), rat Zfand2a (76% identical), chimpanzee ZFAND2A (70% identical), pig ZFAND2A (66% identical), Drosophila melanogaster CG12795 (52% identical), Caenorhabditis elegans aip-1 (43% identical). Paralogues in human: ZFAND2B (60% identical), ZFAND1 (28% identical).
Diseases named in the same sentence as ZFAND2A in open-access papers:
ZFAND2A is named in the same sentence as 5 diseases in open-access papers, as found by Europe PMC text mining. Sharing a sentence is not in itself a finding about the gene and the disease. The quoted sentences say what the papers report.
melanoma (2 papers, 2023 to 2025). A malignant, usually aggressive tumor composed of atypical, neoplastic melanocytes. "The downregulation of ZFAND2A hinders the clonal potential and spheroid growth of melanoma, promoting caspase activation and apoptotic cell death in the absence of drugs." (PMID 40406545, 2025). "Although the effect of ZFAND2A on tumors is still lacking research, previous studies have found that bortezomib significantly induces the expression of ZFAND2A in human melanoma." (PMID 40406545, 2025). "The research results confirm that ZFAND2A is a potential therapeutic target for melanoma, while also highlighting the translational potential of ZFAND2A as a cancer therapeutic target." (PMID 40406545, 2025). "ZFAND2A knockdown regulates the proliferation of melanoma cells." (PMID 40406545, 2025). "The downregulation of ZFAND2A could lead to sensitization to bortezomib, while the upregulation of ZFAND2A could protect melanoma cells from the drug invasion." (PMID 40406545, 2025). "A recent study also identified ZFAND2A/AIRAP as a novel stress-regulated survival factor implicated in the stabilization of the antiapoptotic protein cIAP2 that is highly expressed in several cancers, including melanoma." (PMID 36982814, 2023). "Since ZFAND2A/AIRAP-siRNA-mediated knockdown affects cIAP2 protein stability in melanoma cells, ZFAND2A/AIRAP downregulation markedly enhances bortezomib anticancer activity in melanoma." (PMID 36982814, 2023).
cancer (3 papers, 2013 to 2025). A tumor composed of atypical neoplastic, often pleomorphic cells that invade other tissues. "The results of this study further prove that ZFAND2A plays a significant inhibitory role in the proliferation, migration, and invasion of cancer cells." (PMID 40406545, 2025). "By functionality, we grouped genes according to their function: regulator of energy metabolism (Gadd45a), apoptosis (Bcl2, Ier3), catabolic processes (Zfand2a), inflammation (Klkb1, Tnfrsf14), cell cycle control, and cancer (Csnk2a1, Cdc42, Rasa1, Prdx2, Tpr)." (PMID 36982814, 2023). "Finally, the specific function of ZFAND2A in cancer cell activity was explored in vitro by qRT-PCR, WB analysis, CCK-8, and transwell assay." (PMID 40406545, 2025).
tumor (2 papers, 2013 to 2025). "We found that ZFAND2A increased M1 macrophages, suggesting that ZFAND2A plays a role in killing tumor cells by promoting the M1 phenotype." (PMID 40406545, 2025). "Therefore, we speculated that ZFAND2A might disrupt the tumor progression process during CRC development." (PMID 40406545, 2025). "First, the molecular mechanism of ZFAND2A in CRC immune infiltration and metastasis and the mechanistic pathway of how ZFAND2A overexpression in tumor cells affect macrophages need to be verified experimentally." (PMID 40406545, 2025). "FKBP9L and CCDC108 were found to be significantly increased in tumor tissues, whereas the expression of KRT20, ZFAND2A, and SIRT3 was significantly decreased in tumors." (PMID 40406545, 2025).
ZFAND2A also shares sentences with these, for which no sentence is quoted: Coma (1 paper); schizophrenia (1).